LEP (leptin)
Diseases named in the same sentence as LEP in open-access papers (continued):
Sharing a sentence is not in itself a finding about the gene and the disease.
Obesity (continued). "The increase in IL6 expression during exercise also suppresses hyperphagia and reduces obesity-induced hypothalamic inflammation, thereby promoting insulin and leptin sensitivity and re-establishing balances in the control of appetite and energy homeostasis." (PMID 36986146, 2023). "Both leptin and adiponectin are important in obesity through indirect regulation of food intake and body weight." (PMID 37090773, 2023). "Sleep insufficiency can adversely affect carbohydrate metabolism and levels of endocrine hormones such as insulin, cortisol and leptin, which can lead to changes in appetite and glucose metabolism, accelerating the development of obesity and diabetes." (PMID 37082612, 2023). "In agreement, obesity induced with high-fat diet in mice leads to higher bone marrow adipocyte infiltration and higher leptin levels, with a similar increase of red and white cell precursors." (PMID 37528422, 2023). "Hypothalamic LepRb is downregulated in rodents with high fat diet–induced (HFD-induced) obesity, exacerbating leptin resistance." (PMID 36512408, 2023). "AL HFD feeding induces a positive metabolic state and obesity, and damages the rhythmic synthesis/release of these hormones in the circulation, including ghrelin, leptin, melanocyte-stimulating hormone (α-MSH) and endocannabinoids." (PMID 36825118, 2023). "The imbalance of the circulating leptin and adiponectin levels (leptin/adiponectin ratio, L/A ratio) is an important indicator of metabolic syndromes, such as obesity and diabetes mellitus, and it has a long-term effect." (PMID 36829148, 2023). "It has also been reported that the relationship between obesity and thyroid nodules is probably related to leptin secreted by adipose tissue." (PMID 37152970, 2023). "Overall, our results show that circulating V associates with oxLDL, Co with adiponectin and MPO, Zn with leptin, and Rb with MPO and oxLDL in individuals with obesity and metabolic disorders." (PMID 38075040, 2023). "In obesity, serum leptin levels are high and in vitro studies have shown that serum leptin can induce proliferation of gastric carcinoma cells." (PMID 37928880, 2023). "Our data revealed a relevant impact of obesity per se on the distribution and characteristics of peripheral blood monocyte subsets, with plasma leptin levels, OSAS, and diabetes as crucial amplifying factors." (PMID 36921085, 2023). "In individuals with obesity, the levels of leptin positively correlate with adipose tissue mass, suggesting leptin as a marker of obesity." (PMID 37755259, 2023). "Our study is unique because it focuses solely on dementia and obesity, in its attempt to explain why there is a high prevalence of dementia in the obese population via adiponectin and leptin." (PMID 37363537, 2023). "Female obese mice (253.6 ± 73.67 pg/ml) had higher serum leptin levels than female lean mice (67.19 ± 27.56 pg/ml), indicating that obesity is related to hyperleptinemia." (PMID 37488474, 2023). "The significance of insulin in regulating leptin levels and signaling shows the crucial role of leptin in obesity-induced insulin resistance." (PMID 38068941, 2023). "Deleterious mutations truncate or alter protein function in any of the genes along the leptin-melanocortin pathway, including MC4R, often causing early onset and severe monogenic obesity." (PMID 38002939, 2023). "We genotyped the rs10487505 in DNA samples from 1665 individuals predominantly with obesity and measured leptin mRNA expression in paired samples of AT as well as circulating leptin levels." (PMID 36833305, 2023). "The concept of leptin resistance was proposed several decades ago and continues to be explored for its role in obesity disorders." (PMID 36131285, 2022). "In a follow-up study, we further showed that global TSP-1 deletion abrogates lipid-filled lesion burden and VSMC abundance in ApoE–/– mice treated with recombinant leptin, at concentrations mimicking obesity." (PMID 36505365, 2022).
Obesity (continued). "It is well accepted that in obesity, leptin resistance develops, leading to increased leptin production by adipose tissue and hyperleptinemia in an attempt to compensate for the low leptin responsiveness." (PMID 35215406, 2022). "The following keywords were used in different combinations for the literature search: obesity, adipokines, pathogenesis, leptin, resistin, visfatin, chemerin, DPP-4, adiponectin, omentin, isthmin, nesfatin, preparations, and clinical study." (PMID 36499312, 2022). "Taken together, these findings demonstrate that Fetuin B levels significantly increase with body fat and leptin levels and persist during the progression of obesity." (PMID 35896788, 2022). "The present review highlights the need for holistic approaches including genetics, to establish the connections and boundaries of leptin’s involvement in obesity and CRC, as well as their potential link." (PMID 35563103, 2022). "One crucial step in this direction will be the development of updated and extended reference values for circulating leptin levels during childhood and adolescence including cohorts of children and adolescents with obesity and with extreme obesity." (PMID 35677722, 2022). "This is consistent with the results observed in clinical studies showing a link between obesity/leptin and PTB." (PMID 35326405, 2022). "In rodents, high fat diet overfeeding rapidly, and prior to obesity being measurable, induces neuronal inflammation resulting in insulin and leptin resistance in ARC neurons and subsequently fibrous proliferation of glial cells (gliosis)." (PMID 35834069, 2022). "By IPA, we provide evidence for an impact of the ethnic differences in the expression of 392 miRNAs on three obesity-related canonical pathways, including leptin signaling in obesity, adipogenesis pathway, and white adipose tissue browning pathway." (PMID 36065413, 2022). "Given the relationship between obesity and dementia, some scientists are beginning to investigate a link with leptin." (PMID 35563589, 2022). "In obesity, the accumulation of fat affects adipokines including leptin and adiponectin in adipose tissues." (PMID 35630765, 2022). "Subsequently, before the manifestations of the disease, obesity-induced systemic inflammation will lead to neurodegeneration, which increases with age, where leptin signalling pathways are affected, altering their function." (PMID 35563589, 2022). "Since our research group has determined the obesity-related gene LEP methylation in AML, the LEP methylation pattern in MDS patients has come to our attention." (PMID 35847864, 2022). "Collectively, the present results demonstrated that the orally active peptide YHIEPV derived from a major green leaf protein increased neural leptin responsiveness and reduced body weight gain in mice with dietary obesity." (PMID 35597815, 2022). "Adiponectin and leptin are adipokines that considerably influence obesity-related metabolic diseases by modulating fat metabolism, energy homeostasis, and insulin sensitivity." (PMID 35889740, 2022). "The aim of our project was to establish the Polish database of severely obese children and adolescents and to evaluate the prevalence of monogenic forms of obesity in this cohort, with a special focus on leptin–proopiomelanocortin pathway abnormalities." (PMID 36479220, 2022). "The imbalance of decreased adiponectin plasma concentrations and increased leptin levels is closely related to obesity." (PMID 35990345, 2022). "Correspondingly, some studies signposted that the classes of adipokines, specifically FFA, adiponectin, and leptin, are significant biomarkers and have a vital role in the pathology of obesity." (PMID 36304965, 2022). "After challenge, major differences were observed at latter time points in the levels of insulin, glucose, and leptin, indicating that the regulation of endocrine factors and inflammatory events are largely dysregulated in obesity." (PMID 35406000, 2022).
Obesity (continued). "The methodology was designed to reveal a possible correlation between obesity (quantified by measuring body mass index and waist circumference), the plasma level of leptin, and breast tumor immunohistochemical characteristics." (PMID 35989732, 2022). "Initially described as an anti-obesity hormone, leptin has subsequently been shown to also influence hematopoiesis, thermogenesis, reproduction, angiogenesis, and immune homeostasis." (PMID 36430738, 2022). "Although not discussed in the study, it is interesting to note that circulating leptin levels are increased during obesity alongside with the development of a leptin resistance." (PMID 36569860, 2022). "Of great relevance within the scope of obesity, but largely understudied, is the potential impact of altered local leptin signalling on mitochondrial function in the oocyte from obese mothers." (PMID 36855701, 2022). "Leptin, a hormone having the ability to reduce the intake of food and body weight, was initially considered for use in the treatment of obesity." (PMID 35159361, 2022). "Obesity can lead to chronic inflammation in different tissues, generating insulin and leptin resistance and alterations in glucose and lipid metabolism, favoring the development of degenerative diseases, including type II diabetes." (PMID 35112705, 2022). "Recent studies have shown that leptin inhibited apoptosis and increased proliferation in obesity-related cancer cell lines, including EAC." (PMID 35409299, 2022). "This study observed a strong association between the LEP 19A variant with obesity related variables such as BMI, waist circumference, WHR, and body fat percentage in both obesity and control groups." (PMID 36619235, 2022). "Upon HFD, mice developed obesity as well as leptin and insulin resistance, which were prevented by TEL." (PMID 35431918, 2022). "Obesity directly drives adipocyte cells towards inflammatory phenotypes, releasing pro-inflammatory cytokines, such as leptin, IL-6, IL-10, TNF-α." (PMID 35069893, 2022). "Mistimed eating can also result in the dysregulation of hormones involved in energy metabolism (such as leptin, cortisol, adiponectin, pro-opiomelanocortin, gastric inhibitory polypeptide and others), which can in turn promote obesity." (PMID 36135220, 2022). "We detected alterations in gene expression associated with obesity and related parameters, i.e., BMI SDS, adipocyte size, macrophage infiltration, adiponectin, and/or leptin." (PMID 35457174, 2022). "Our results confirm the dysregulation for some peptide hormones (leptin and ghrelin) and point out further controversy for other hormones with respect to obesity, insulin resistance and dyslipidemia." (PMID 36355134, 2022). "In conclusion, we present a novel iPRTi strategy for in vivo protein knockdown by oral administration of recombinant yeast, which was demonstrated to be effective for partial leptin reduction and diet-induced obesity control." (PMID 35774455, 2022). "Further, elevated ceramide levels appear to worsen leptin resistance, which is important in the pathophysiology of obesity and metabolic syndrome." (PMID 36353888, 2022). "During obesity, adipose tissue increases leptin secretion and suppresses satiety, promoting gluconeogenesis and hepatic insulin resistance." (PMID 35422689, 2022). "Elevated leptin in serum induces activation of Stat3 in cartilage and leads to pathological activation of CD14/TLR4, which further provokes obesity-associated inflammation and MMP-13 expression." (PMID 35548357, 2022). "Biological sex and aging impact obesity development and type 2 diabetes, changing the secretion of leptin and adiponectin." (PMID 36615734, 2022). "Leptin levels increased three times more rapidly with progressive obesity in females, as measured either according to BMI or percentage body fat." (PMID 35637895, 2022).
Obesity (continued). "Individuals with obesity experience an increase in the size and the number of adipocytes, which function as an endocrine organ and release various adipocytokines such as leptin and adiponectin that exert wide ranging effects on other cells." (PMID 36466818, 2022). "Along these lines, reduction of bioactive leptin levels in the context of obesity induces leptin sensitization and improves leptin action." (PMID 36394061, 2022). "Leptin has an important role in the regulation of energy balance and glucose metabolism and is considered to play an important part in the link between obesity and EC." (PMID 36505829, 2022). "The expression patterns of miRNAs related to leptin and adiponectin, including miR-222, miR-103, miR-17, miR-let-7a, and miR-let-7c, were different in mothers with overweight and obesity compared to those in mothers with normal weight." (PMID 36313069, 2022). "High leptin levels are an important manifestation of obesity, and children and adolescents show increased leptin levels with increasing body fat mass." (PMID 35498804, 2022). "The beneficial effect of exogenous oxytocin was also observed in persons with leptin-resistant obesity." (PMID 35806096, 2022). "Leptin acts on the hypothalamus to regulate food intake and energy expenditure and is known to be elevated in obesity." (PMID 35662920, 2022). "Over an extended period of unregulated T2DM, the body develops a lower sensitivity towards leptin, and becomes resistant to the hormone, reducing its ability to distinguish between satiety and overeating, encouraging the advancement of obesity and BMAT." (PMID 35887957, 2022). "The mean serum leptin level in the obesity group with dominant homozygous AA genotype (56.6 ng/ml) was found to be high when compared with other obesity groups with AG (42.8 ng/ml) and GG (49.3 ng/ml) genotypes." (PMID 36619235, 2022). "Leptin is suggested to be pro-inflammatory adipokine, which is a major stimulus for the production of aldosterone in obesity, leading to promoted TNF-α production and macrophages activation." (PMID 36579524, 2022). "Animal studies demonstrated that obesity and leptin reduced orthodontic tooth movement by affecting osteoclastogenesis." (PMID 36142638, 2022). "Since dysregulated leptin and adiponectin secretions were reported to be one of the links among obesity, insulin resistance and neurodegenerative disorders, we measured plasma levels of these adipokines in the different animal groups." (PMID 35215406, 2022). "Especially in individuals with obesity, leptin leads to an increased secretion on IFNγ and suppression of Th2." (PMID 35844529, 2022). "The latest report declaimed “Less Is More,” a model explaining that partial leptin reduction triggers leptin sensitization and contributes to obesity control." (PMID 35774455, 2022). "In this study we observed significant difference in the fasting plasma peptide hormones among the obese and normal weight Lebanese individuals with a notable relationship between leptin, glucose, and obesity markers." (PMID 36355134, 2022). "Adipose secretome, including two of the most abundant and well-studied adipokines, leptin and interleukin-6, is involved in the regulation of energy metabolism and obesity-related low-grade inflammation." (PMID 35631195, 2022). "Ghrelin levels are known to inversely correlate with measures of obesity, including BMI, percent body fat, and circulating levels of both insulin and leptin." (PMID 35454071, 2022). "At the same time, PPARγ is related to the regulation of obesity factors, such as ADPN and LEP; changes in obesity factors are the best predictors of insulin sensitivity." (PMID 35407014, 2022). "Underlying all of these proposed mechanisms to explain the development of leptin resistance, however, are obesity-related defects in the saturable transport of leptin across the blood-brain barrier (BBB) into the CNS." (PMID 35527735, 2022).
Obesity (continued). "At the same time, certain infectious and inflammatory stimuli, such as lipopolysaccharide (LPS), IL1, and TNF-α, can also increase leptin levels, which correlate with the chronic inflammation in obesity." (PMID 36235638, 2022). "A common example of this is the tendency of the hypothalamus to develop leptin resistance during obesity." (PMID 36499772, 2022). "Similar to WAT, MAT also acts as a large endocrine organ that secretes leptin and adiponectin, which increase or decrease under pathological conditions such as osteoporosis, diabetes, and obesity." (PMID 36012601, 2022). "Pro-obesity gut microbiota was found to reduce leptin sensitivity and the expression of proglucagon." (PMID 35204214, 2022). "Leptin resistance, which is characterized by elevated circulating levels of leptin and reduced leptin sensitivity, is not only a phenomenon of obesity, but also contributes to the development and maintenance of obesity." (PMID 36547931, 2022). "Obesity-related leptin resistance influences overall brain health, as increasing evidence supports a link between obesity and neurodegenerative disease (see Leptin and Neurodegenerative Disorders Section)." (PMID 35784728, 2022). "Such a complex set of actions, alongside the inherent intricacies of ovarian function regulation, portrays leptin as a key but challenging signalling system to study during obesity." (PMID 36855701, 2022). "Of note, leptin––a classic adipokine––was exclusively increased in the hASC‐CM of the OA group, suggesting that aging counteracts the impact of obesity on leptin secretion." (PMID 35811457, 2022). "Both obesity models exhibited higher body weight, adiposity, glucose, insulin, and leptin blood levels compared with control mice." (PMID 35023323, 2022). "Elevated fatty acids in obesity inhibits CD8+ Teff cell glycolysis through the leptin-PD-1-STAT3-FAO pathway, thereby restricting CD8+ T cell antitumor functions." (PMID 39872079, 2022). "Leptin, adiponectin, estrogen, and several pro-inflammatory cytokines are involved in the development of obesity-driven BC through the activation of multiple oncogenic and pro-inflammatory pathways." (PMID 35814391, 2022). "Obesity decreases adiponectin levels, an adipokine that counters the cancer-promoting effects of leptin." (PMID 35326592, 2022). "In an obesity state, leptin levels are higher, but leptin activity is lower due to leptin resistance." (PMID 36431836, 2022). "Impaired leptin-mediated regulation with leptin resistance, which probably results from high plasma leptin levels and declined WAT, induces abnormal hypothalamus-related activity and elevated obesity and serum leptin with age." (PMID 35379822, 2022). "Nevertheless, further studies are needed to obtain better insight in the relationship between leptin and asthma in obesity." (PMID 36613991, 2022). "Most noteworthy in this study, however, was the localization of immuno-reactivity in the hypothalamus of DIO mice, via a conduit that is closed to leptin in this rodent model, and in most cases of human obesity." (PMID 35527735, 2022). "Obesity affects the concentration of both hormones—in obese people, lower ghrelin values and an increase leptin concentration are observed." (PMID 35327129, 2022). "Leptin, a hormone that is capable of effectively reducing food intake and body weight, was initially considered for obesity treatment." (PMID 35281054, 2022). "Leptin is a peptide hormone that controls food intake and energy expenditure by sending signals to the brain, especially the hypothalamus, to reduce obesity and its complications." (PMID 35937803, 2022). "Some of the common features between the sexes of obesity-induced CRC include increased levels of leptin, IL-6, insulin, and C-reactive proteins (CRP-1), and decreased adiponectin levels." (PMID 36429114, 2022). "Leptin is considered a biomarker for obesity as the levels of leptin are directly proportional to body fat mass accumulation." (PMID 35757435, 2022).